NEDD4 (NEDD4 E3 ubiquitin protein ligase)
Diseases named in the same sentence as NEDD4 in open-access papers (continued):
Sharing a sentence is not in itself a finding about the gene and the disease.
prostate carcinoma (23 papers, 2014 to 2025). A carcinoma that arises from epithelial cells of the prostate gland. "Cumulative evidence suggests that NEDD4 is linked to tumor progression in several human cancers, such as gastric carcinoma, hepatoma carcinoma, bladder cancer, and prostate cancer." (PMID 31856858, 2019). "It is also imperative to investigate the associations of protein levels of AR variants, PMEPA1-b and NEDD4 in prostate cancer tissue samples, which further required to generate the PMEPA1 isoform specific antibodies to distinguish the amino acid sequence differences within N-terminus." (PMID 32842649, 2020). "Mutant NEDD4-1 that evades this degradation enhances the growth and migration of breast and prostate cancer cells by reducing PTEN levels." (PMID 40535763, 2025). "The active component of fenugreek, diosgenin, downregulates NEDD4 and induces apoptosis in PC-3 prostate cancer cells through pAkt suppression and p73 activation." (PMID 41346617, 2025). "An in vitro study showed diosgenins’ anti-tumor and apoptotic effects in PC-3 prostate cancer via downregulation of NEDD4 and modulation of pAkt, P73 and LATS1." (PMID 41346617, 2025). "Diosgenin, a steroidal saponin, was found to also have similar effects on NEDD4 in prostate cancer cells." (PMID 35204725, 2022). "Neural precursor cell express NEDD4 (NEDD4 E3 ubiquitin protein ligase), an E3 ligase with a tumor-promoting role in prostate cancer." (PMID 35317831, 2022). "For example, diosgenin down-regulates NEDD4 expression to decrease growth and motility of prostate cancer cells." (PMID 31881805, 2019). "It has been reported that NEDD4 plays an important role in facilitating the progression of breast and prostate cancers." (PMID 24657926, 2014). "Also, the association of Nedd4 and IRS2 through monoubiquitination has been reported to activate IGF-1 signaling and induce cell proliferation in prostate cancer cells." (PMID 38272982, 2024). "Similarly, shRNA inactivation of NEDD4 increases HER3 levels in prostate cancer cells, increasing HER3 signaling and cancer cell growth." (PMID 36293239, 2022). "Interestingly, in PC-3 prostate cancer cells, the NEDD4 and IRS-2 connection is also essential for optimal IGF-1 signaling activation and cell proliferation." (PMID 36293239, 2022). "Moreover, diosgenin, a saponin produced from the Trigonellafoenum graecum plant, inhibited NEDD4 expression in prostate cancer cells, resulting in anticancer action." (PMID 36293239, 2022). "In addition, NEDD4 was also found to be androgen responsive in hormone responsive prostate cancer cells." (PMID 32842649, 2020). "Diosgenin exerted its anticancer function via downregulation of NEDD4 in prostate cancer cells." (PMID 33288736, 2020). "The E3 ubiquitin ligase NEDD4 is a negative regulator of HER3 level and signaling, and NEDD4 expression was inversely correlated with HER3 levels in prostate cancer clinical samples, and its expression was suggested to serve a biomarker for HER3 targeted antibody cancer therapies." (PMID 28036286, 2017). "Interestingly, NEDD4 has been shown to negatively regulate the stability of AR in prostate cancer cells." (PMID 25823820, 2015). "Several preclinical studies revealed that NEDD4 has cancer chemopreventive and therapeutic capabilities against various malignancies, which include solid tumors such as brain, breast, colon, bladder, liver, pancreas, prostate cancers, etc., and hematological cancers such as lymphoma and leukemia." (PMID 36293239, 2022). "It has shown that autophagy was suppressed in lung and prostate carcinoma cell lines when NEDD4 was knocked out and this NEDD4 downregulation significantly increased activated mTOR (p-mTOR) levels, implying that mTOR signaling was involved in NEDD4-mediated autophagy." (PMID 36293239, 2022). "In conclusion, NEDD4 could be a possible target for the therapy of prostate cancer." (PMID 36293239, 2022).
prostate carcinoma (continued). "Moreover, in breast and prostate cancer cells, NEDD4 might enhance cell proliferation and migration by regulating the PTEN/Akt signaling pathway." (PMID 36293239, 2022). "Knockdown of NEDD4-1 enhances HER3-driven migration and proliferation of breast and prostate cancer cells, and promotes the growth of BC graft tumors." (PMID 40535763, 2025). "Nedd4 is known to function as an oncogenic protein, and we showed that Nedd4 is required for IGF-I-induced proliferation of prostate cancer cells." (PMID 26074875, 2015). "A negative link was discovered between HER3 and NEDD4 levels in the DU145 prostate cancer cell lines." (PMID 36293239, 2022). "The E3 ubiquitin ligase NEDD4 (also known as NEDD4-1) has been reported to negatively regulate PTEN protein levels through poly-ubiquitination and proteolysis in carcinomas of the prostate, lung, and bladder, but its effect on PTEN in the breast has not been studied extensively." (PMID 26276352, 2016). "Aronchik and his colleagues reported that indole-3-carbinol (I3C), a compound derived from cruciferous vegetables, could inhibit the functions of NEDD4-1 and WWP1 through targeting the HECT domain, thus abrogating the proliferation and metastasis of melanoma or prostatic carcinoma." (PMID 35264565, 2022). "Our earlier studies defined a mechanistic model for male hormone dependent regulation of AR protein levels in prostate cancer (CaP) cells through a negative feed-back loop between AR and PMEPA1, an androgen induced NEDD4 E3 ubiquitin ligase binding protein." (PMID 25883222, 2015).
melanoma (22 papers, 2017 to 2025). A malignant, usually aggressive tumor composed of atypical, neoplastic melanocytes. "High NEDD4 expression in melanoma tissue is associated with poor patient prognosis and promotes tumor progression by inhibiting T-cell-mediated killing of melanoma cells." (PMID 38535990, 2024). "On the other hand, a low expression of NEDD4-1 in cancer cells, like melanoma, was found to be associated with the activation of the immunoglobulin-containing and Proline-rich receptor-1 (IGPR-1)–mediated autophagy." (PMID 36918822, 2023). "The specific mechanism was identified as Nedd4‐mediated ubiquitination of VDAC2/3 in melanoma, which plays a crucial role in ferroptosis." (PMID 38634270, 2024). "Nedd4 can be induced upon erastin treatment in melanoma cells, and Nedd4 leads to VDAC 2/3 ubiquitination and mitochondrial pore degradation." (PMID 37607902, 2023). "In line with this, a study showed that indole-3-carbinol (I3C) disruption of NEDD4 ubiquitination activity caused the wild-type PTEN tumor suppressor to stabilize and induced an antiproliferative response in melanoma." (PMID 36293239, 2022). "Western blot analysis revealed that overall there is an inverse correlation between IGPR-1 and NEDD4 in four different melanoma cell lines." (PMID 33962630, 2021). "To answer this question, we knockdown NEDD4 via shRNA strategy in A375 cell line which has highest levels of NEDD4 expression compared to three other melanoma cell lines." (PMID 33962630, 2021). "NEDD4 was reported to degrade VDAC2/3 via the UPS to inhibit the sensitivity of melanoma cells to erastin." (PMID 34869326, 2021). "In the past few years, some actors have been identified as crucial players in melanoma drug resistance, like NEDD4." (PMID 33800394, 2021). "In melanoma cells, NEDD4 degraded VDAC2/3 via the ubiquitin-proteasome system (UPS) to inhibit the sensitivity to erastin." (PMID 34869326, 2021). "The depletion of NEDD4 was found to promote the ferroptosis induced by erastin by limiting the degradation of VDAC2/3 in melanoma." (PMID 34277151, 2021). "The observed effects of Nedd4 on the protein degradation of VDAC2/3 suggest that the expression level of Nedd4 should modulate erastin sensitivity in melanoma cells." (PMID 31974380, 2020). "Here, we report that erastin activates the transcriptional expression of Nedd4 through FOXM1 in melanoma cells." (PMID 31974380, 2020). "Here we identified VDAC2 and VDAC3 as two substrates of Nedd4 during erastin-induced ferroptosis in melanoma cells." (PMID 31974380, 2020). "Together, we identify an E3 ligase that regulates ferroptosis in melanoma cells and provide further insight into Nedd4 as a target for overcoming erastin-induced resistance to cancer therapy." (PMID 31974380, 2020). "The NEDD4-1-PTEN axis is implicated in the progression of non-small-cell lung cancer, breast cancer, glioblastoma, prostate cancer, pituitary adenoma, pancreatic ductal adenocarcinoma, bladder cancer, melanoma, and gastric cancer." (PMID 40002221, 2025). "While STARD1 is not directly regulated by ubiquitination it is stabilised by VDAC2, a protein in the outer mitochondrial membranate that is ubiquitinated by Nedd4 in melanoma cells, a HECT E3 ligase with high sequence homology in the interacting WW domains to Itch." (PMID 38216558, 2024). "Interestingly, it was found that anti-tumor immunity mediated by T cells against melanoma cells is inhibited when NEDD4 is overexpressed." (PMID 36293239, 2022). "In A375 melanoma cell lines, erastin, a ferroptosis activator, stimulates the expression of NEDD4 and FOXM1 that leads to the ubiquitination and degradation of voltage-dependent anion channels, VDAC2/3, which further leads to the suppression of erastin-induced ferroptosis in melanoma." (PMID 36293239, 2022).
melanoma (continued). "In addition, treatment of indole-3-carbino (I3C), a naturally occurring compound found in cruciferous vegetables, along with knockdown of NEDD4, inhibited degradation of wild-type PTEN, causing antiproliferation in melanoma cells." (PMID 36293239, 2022). "In A375 melanoma cell lines, erastin, a ferroptosis activator, stimulates NEDD4 and FOXM1 expression, and it led to the ubiquitination and degradation of voltage-dependent anion channels, VDAC2/3, which further led to the suppression of erastin-induced ferroptosis in melanoma." (PMID 36293239, 2022). "Knockdown of NEDD4 increased IGPR-1 levels in A375 melanoma cells." (PMID 33962630, 2021). "To test whether Nedd4-mediated VDAC2/3 degradation is also essential for the suppression of erastin-induced ferroptosis in melanoma cells carrying wt BRAF, we knocked down Nedd4 or overexpressed VDAC2/3 in MeWo cells." (PMID 31974380, 2020). "Thus, NEDD4-1 inducers can be useful treatments for IGPR-activated cancer cells such as melanoma." (PMID 36918822, 2023). "In melanoma cells, the downregulation of Nedd4 by shRNA rescues the elimination of VDAC2/3 proteins induced by erastin and increases the sensitivity of melanoma cells to erastin, thereby regulating ferroptosis in melanoma cells." (PMID 40509137, 2025). "Another study demonstrated that NEDD4 ubiquitinates immune checkpoint GITR and can promote melanoma cell proliferation by suppressing anti-tumor immune responses mediated by T cells." (PMID 36293239, 2022). "A melanocytic transmembrane protein called Melan-A/MART-1 interacts with NEDD4 and ITCH and thus becomes ubiquitylated in melanoma cells." (PMID 36293239, 2022). "For example, knockdown of Nedd4 inhibits VDAC2/3 protein degradation, thereby increasing the sensitivity of melanoma cells to the ferroptosis inducer erastin." (PMID 36399105, 2022). "The knockdown of NEDD4 increased the VDAC2/3 protein level, with a consequent improvement of erastin sensitivity in melanoma cell lines and in the mice xenograft model." (PMID 33800394, 2021). "Collectively, these findings suggest that FOXM1 inhibits ferroptosis by regulating Nedd4 expression and subsequent VDAC2/3 degradation in melanoma cells." (PMID 31974380, 2020). "Knockdown of Nedd4 leads to elevated protein level of VDAC2/3, which increased the sensitivity of melanoma cells to erastin both in vitro and in vivo." (PMID 31974380, 2020). "Downregulation of Nedd4 by shRNA rescued erastin-induced protein elimination of VDAC2/3 and increased the sensitivity of melanoma cells to erastin." (PMID 31974380, 2020). "Taken together, these results support the idea that Nedd4 and VDAC2/3 play essential roles in regulating erastin-induced ferroptosis in different subtypes of melanoma cells." (PMID 31974380, 2020). "Indole-3-carbinol had antiproliferative effects via binding with NEDD4 and subsequently impairing PTEN degradation in melanoma cells." (PMID 33288736, 2020). "Other alterations were found in genes reportedly altered in skin cancer, such as DGKI and SYK in melanoma or BCOR, PIKFYVE and NEDD4 in SCC." (PMID 28410231, 2017). "In melanoma cells, the FOXM1 could inhibit ferroptosis via regulating the expression of Nedd4 and the degradation of VDAC2/3." (PMID 38382091, 2024). "Indeed, the inhibition of NEDD4 ubiquitination activity promotes the PTEN stabilization, which can induce an antiproliferative response in melanoma." (PMID 33800394, 2021). "NEDD4 binds to and mediates polyubiquitination of IGPR-1 leading to its lysosomal-dependent degradation, suggesting a significant role for NEDD4 in modulating IGPR-1 expression in melanoma and other human cancers." (PMID 33962630, 2021). "Small molecules such as Heclin (a non-specific HECT E3 inhibitor) and Indole-3-carbinol (I3C; inhibitor against NEDD4-1 and WWP1 catalytic HECT domains) are capable of stabilizing PTEN, reducing Akt phosphorylation, and impairing cell viability in models of gastric cancer and melanoma." (PMID 40002221, 2025).
melanoma (continued). "However, neither downregulation nor overexpression of Nedd4 had a significant effect on RSL3-induced ferroptosis in melanoma cells." (PMID 31974380, 2020).
colorectal cancer (19 papers, 2013 to 2023). A primary or metastatic malignant neoplasm that affects the colon or rectum. "NEDD4, CNOT6L, and DNA repair protein RAD51 homolog 2 (RAD51B) were previously associated with IBD, tuberculosis, and colorectal cancer, respectively." (PMID 37512987, 2023). "Nevertheless, NEDD4 was shown to promote proliferation of colorectal cancer cells in a PI3K/PTEN/Akt pathway-independent manner." (PMID 36774408, 2023). "Increased expressions of NEDD4 has been identified by immunohistochemical staining in gastric and colorectal cancer, hepatocellular carcinoma, non‐small‐cell lung carcinoma, invasive ductal carcinoma, and endometrial adenocarcinoma." (PMID 35639915, 2022). "A study revealed that NEDD4 was found to be expressed in 80 percentage of colorectal carcinomas and has tumorigenic activity by inducing ubiquitination and degradation of the PTEN gene." (PMID 36293239, 2022). "N-myc downstream-regulated gene 1 (NDRG1) inhibits colorectal cancer cell proliferation through emulatively antagonizing NEDD4-mediated ubiquitylation of p21, which suggests an oncogenic role of NEDD4 in colorectal cancer." (PMID 33767993, 2021). "For example, p21 is the substrate of NEDD4 as well as a key regulator of tumor proliferation in colorectal cancer." (PMID 33767993, 2021). "Later observations linked RAS activation to NEDD4 overexpression and subsequent PTEN degradation in human colorectal cancer." (PMID 31001145, 2019). "NEDD4 has been previously found to be overexpressed in colorectal cancers and promoted growth of colon cancer cells." (PMID 24657926, 2014). "Recently, it is reported that NEDD4-1 is highly expressed in a wide variety of tumors, such as colorectal cancer, bladder cancer, gastric carcinoma and involved in cancer cell growth." (PMID 24340059, 2013). "For example, NEDD4-1 is highly expressed in a wide variety of tumors, such as colorectal cancer, bladder cancer, gastric carcinoma." (PMID 24340059, 2013). "In addition, NEDD4 is overexpressed in colorectal cancer and promotes colonic cell growth independently of the PI3K/PTEN/AKT pathway." (PMID 31856858, 2019). "It has been shown to participate in the ubiquitination of the tumor suppressor gene PTEN, which in turn suggest that NEDD4 might have a pro-oncogenic role NEDD4 was found to be overexpressed in colorectal cancers and promoted tumor cell growth." (PMID 28423617, 2017). "NEDD4 mRNA was significantly increased in all stages of colorectal cancer." (PMID 24312311, 2013). "In human malignancies such as gastric, colorectal cancer, NSCLC (non-small-cell lung carcinoma), hepatocellular carcinoma, and others, NEDD4 is commonly overexpressed and is an important factor in medication resistance during cancer treatment." (PMID 37605223, 2023). "NEDD4 overexpression and its role in cancer growth promotion (independently of PTEN and PI3K/AKT signaling) were shown in colorectal cancers, in prostate and bladder cancer, and indirectly in esophageal cancer." (PMID 28423617, 2017). "Recently, NEDD4 mRNA was reported to be overexpressed in colorectal cancer, but tumor stage was not considered in the analysis." (PMID 24312311, 2013). "Additionally, high NEDD4 expression predicts a poor prognosis in different types of tumors including LUAD, hepatocellular carcinoma, gastric cancer, and colorectal cancer." (PMID 35646490, 2022).
gastric cancer (19 papers, 2013 to 2025). A primary or metastatic malignant neoplasm involving the stomach. "Previous work has demonstrated that NEDD4 is associated with poor survival in gastric carcinoma and hepatocellular cancer." (PMID 31856858, 2019). "NEDD4 has also been demonstrated to be involved in the resistance of tumor cells, including gastric cancer, glioblastoma and skin cancer cells, to chemotherapy." (PMID 39890782, 2025). "As for gastric cancer, NEDD4 was found to be overexpressed in gastric cardia adenocarcinoma, which is closely related to poor prognosis." (PMID 36774408, 2023). "Further, Decitabine, a DNA methylation inhibitor, increased migration and invasion of gastric cancer cells by increasing the expression of NEDD4." (PMID 36293239, 2022). "Knockdown of NEDD4 severely impaired EGF-stimulated gastric cancer cell migration and invasion, suggesting that NEDD4 mediates migration and invasion signaling of EGFR." (PMID 29455656, 2018). "In human gastric cancer, down‐regulation of FOXA1 by the E3 ligase ZFP91 has been associated with promotion of chemoresistance, while in colon cancer down‐regulation of FOXA1 via NEDD4 promoted EMT and metastasis." (PMID 37491794, 2023). "NEDD4 E3 ligase family genes presented high expression in some tumors including pancreas cancer, esophagus cancer, gastric cancer and colon cancer; while NEDD4 E3 ligase family genes showed low expression in certain tumors of kidney, thyroid, and testis cancer." (PMID 37291499, 2023). "Knockdown of NEDD4 by shRNA completely impairs cell migration and invasion of gastric cancer cells." (PMID 34833029, 2021). "The expression level of NEDD4 was decreased from gastric dysplasia to gastric carcinoma." (PMID 33767993, 2021). "In gastric carcinoma, the role of NEDD4 is equally controversial." (PMID 33767993, 2021). "Knockdown of NEDD4 in gastric cancer cells severely impaired cell migration and invasion." (PMID 29455656, 2018). "It was also shown that NEDD4 mediates EGF-dependent AGS and N87 gastric cancer cell line invasion and migration via EGFR-mediated metastasis signaling." (PMID 36293239, 2022). "Both NEDD4 and CYR61 functionally promote gastric cancer cell migration and invasion, suggesting that both NEDD4 and CYR61 are driver proteins for metastasis." (PMID 30976198, 2019). "Our previous study observed that the HECT E3 ubiquitin ligase NEDD4 is significantly correlated with tumor metastasis and required for migration and invasion signaling of EGFR in gastric cancer cells." (PMID 29455656, 2018). "For instance, NEDD4, a classical member of the HECT family, has been reported to play an oncogenic role in the diversity of carcinomas, such as breast, lung, bladder, and gastric cancers." (PMID 35264565, 2022). "Interestingly, another study showed NEDD4 to be important in gastric cardia adenocarcinoma (GCA) metastasis, as the shRNA-mediated NEDD4 decrease in AGS and N87 gastric cancer cells impairs basal and EGF-stimulated cell invasion and migration." (PMID 36293239, 2022).